STAT3 (signal transducer and activator of transcription 3)
Diseases named in the same sentence as STAT3 in open-access papers (continued):
Sharing a sentence is not in itself a finding about the gene and the disease.
prostate carcinoma (continued). "B cell–derived lymphotoxin can also activate I kappa B kinase (IKK)-α and signal transducer and activator of transcription 3 (STAT3) signaling to promote prostate cancer progression." (PMID 30521597, 2018). "It efficiently antagonizes the hepatocyte growth factor (HGF)-stimulated c-Met/STAT3 activation, as well as proliferation and colony formation in refractory prostate cancer cells." (PMID 30563284, 2018). "We found that IATL reduced the growth of prostate cancer cells through increased production of ROS, activation of ER stress pathway, and inhibition of STAT3." (PMID 30541589, 2018). "Taken together, our study provides proof-of-principle that STAT3 inhibition using galiellalactone is a viable treatment option as monotherapy in ENZR prostate cancer as well as a logical strategy for combination therapy with ENZ in CRPC." (PMID 30470788, 2018). "Signal transducer and activator of transcription 3 (STAT3) is an oncogenic transcription factor that is constitutively activated in many types of solid tumors, including prostate cancer." (PMID 30541589, 2018). "In fact, apart from CLU, also CEBPB and D seem to play a role in PC proliferation, as interleukin-6 (IL-6) treatment increases the expression of CEBP-D family member, inducing IL-6/STAT3-dependent growth arrest on prostate cancer cells in vitro." (PMID 29562723, 2018). "In conclusion, our findings have shown that ginsenoside Rh2 induces prostate cancer DU145 cells apoptosis through up-regulation of PPAR-delta which leads to down-regulation of p-STAT3/STAT3 and intracellular oxidative stress." (PMID 29541400, 2018). "Given the wide involvement in various pathways, STAT3 can be an important signaling component in prostate carcinoma (PCa); efforts aimed at targeting this protein for cancer treatment are steadily increasing." (PMID 29854771, 2018). "In contrast, the EZH2 component of the polycomb complex 2 operates K180 tri-methylation, which was shown to be required to maintain STAT3 YP and transcriptional activity in the cells from glioblastoma and prostate cancer." (PMID 30231582, 2018). "According to these findings, scoparone exerted an anti-prostate cancer effect by inhibiting STAT3 activity." (PMID 29495626, 2018). "Treatment of mice bearing human prostate cancer xenografts with IATL was also associated with induction of ER stress and inhibtion of STAT3." (PMID 30541589, 2018). "In a previous study, CT inhibited STAT3 Tyr705 phosphorylation in DU145 prostate cancer cells by binding to the SH2 domain of STAT3 and blocking the formation of STAT3 dimers." (PMID 28157698, 2017). "In particular, the IL-6/STAT3 signaling pathway appears to be crucial for the progression of prostate cancer." (PMID 28467474, 2017). "Several early reports demonstrated that down-regulation of STAT3 suppressed the growth of prostate cancer cells." (PMID 28783760, 2017). "One of the main targets of Ref-1/APE1 redox signaling in prostate cancer is STAT3, which is constitutively active in prostate cancer." (PMID 28825044, 2017). "Our qPCR resulted showed that resveratrol down regulate miR-21 expression in prostate cancers cells, presumably by suppressing STAT3." (PMID 28467474, 2017). "Skp2 is a transcriptional target of STAT3, which, along with downstream genes (including RhoA), can stimulate prostate cancer metastasis and proliferation." (PMID 28157698, 2017). "In pancreatic and prostate carcinomas, such complexes contain STAT3, HIF-1α, CREB-binding protein (CBP/p300), and redox effector factor-1/apurinic/apyrimidinic endonuclease (Ref-1/APE)." (PMID 28978186, 2017). "IL-6 acts through the Janus kinase (JAK)–signal transducer and activator of transcription (STAT) pathway and anti-STAT3 approaches have been proposed in several human cancers, including prostate cancer." (PMID 29214142, 2017). "Recent reports indicate that increased constitutive and IL-6-induced STAT3 activation is common in prostate cancer cell lines and tissues." (PMID 27458171, 2017).
prostate carcinoma (continued). "It has been reported that inhibition of STAT3 partially contributes to the proapoptotic effect of SFN in prostate cancer cells." (PMID 28054986, 2017). "For instance, G-CSF was reported to promote survival and growth of bladder cancer cells by stimulating STAT3-depedent survivn expression, and to potentiate tumor progression through its neurotrophic ability on nerve in prostate cancer." (PMID 29050255, 2017). "Since IL-6 signaling pathway includes STAT3, we performed Western blot studies to assess the status of p-STAT3 in the different prostate cancer cell lines following IL-6 treatments." (PMID 28467474, 2017). "Transfection with PTPε siRNA reversed the Capz-induced inhibition of STAT3 activation and increase in apoptosis, further suggesting that PTPε plays a critical role in Capz-induced inhibition of prostate cancer cell growth and survival." (PMID 27458171, 2017). "Regarding MDSCs, recent studies demonstrated that SOCS3 negatively regulates the development and function of MDSCs via inhibition of STAT3 activation in prostate cancer." (PMID 29326716, 2017). "Based on the evidence, both STAT3 and survivin present as prime targets for anti-prostate cancer therapies." (PMID 28825044, 2017). "Skp2 is overexpressed in human prostate cancers, which exerts critical downstream effects on STAT3 in human prostate cancer." (PMID 28157698, 2017). "Down-regulation of PCAT29 was associated with increased STAT3 and decreased levels of PDCD4 (a downstream target of miR-21) in Grade 4 prostate cancer." (PMID 28467474, 2017). "Collectively, these data suggest that aberrant STAT3 activation occurs often in prostate cancer and is strong predictor of poor prognosis in patients." (PMID 27458171, 2017). "Diallyl trisulfide, the cancer chemopreventive constituent of garlic, inhibits phosphorylation of Stat3 in prostate cancer cells in culture and in vivo." (PMID 29056905, 2017). "In prostate cancer cells, morusin suppressed cell viability and induced apoptosis by suppressing the STAT3 pathway." (PMID 28915664, 2017). "In our results, the cultured medium of the THP-1 cells stimulated the migration of prostate cancer cells, activated the migration of STAT3 into the chromatin fraction, and induced p-STAT3 protein expression in DU145 cells." (PMID 28157698, 2017). "Our previous study demonstrated that DT inhibits the tumor-promoting ability of macrophages in prostate cancer through the inhibition of the CCL2/STAT3 axis." (PMID 29207614, 2017). "First, enzalutamide is capable of activating STAT3 in all three prostate cancer cell lines evidenced by the elevated levels of phosphorylated STAT3 (pSTAT3) without affecting the total levels of STAT3." (PMID 28837141, 2017). "IL-6 protects prostate cancer cells against apoptosis through activation of signal transducer and activator of transcription 3 (STAT3) and phosphatidylinositol-3 kinase (PI3K)." (PMID 28292326, 2017). "We investigated the effect of Capz on STAT3 activation and downstream proteins in human prostate cancer cells and a xenograft mouse model." (PMID 27458171, 2017). "We previously reported the content of endogenously expressed activated form of signal transducer and activator of transcription 3 (phospho-STAT3, p-STAT3) in prostate cancer cells." (PMID 27435207, 2016). "Inhibitors of STAT3 efficiently radiosensitized esophageal-, head and neck squamous cell carcinoma and prostate cancer cells and inhibited both hypoxia/radiation-induced activation of STAT3 and upregulation of HIF-1α and VEGF expression." (PMID 27029037, 2016). "STAT3 is activated in a broad spectrum of human cancers, such as prostate cancers, breast cancer, and nasopharyngeal carcinoma, and has been implicated as a potential therapeutic target for multiple human cancers." (PMID 27649234, 2016). "In prostate cancer cell lines downregulation of the AR increases STAT3 signaling, which is required for CSC maintenance." (PMID 26880966, 2016).
prostate carcinoma (continued). "Unpublished data from our group also indicate that nimbolide can substantially abrogate the activation of another important oncogenic transcription factor, signal transducer and activator of transcription 3 (STAT3) in diverse prostate cancer cells." (PMID 27027349, 2016). "Based on this observation IL-6/STAT3 signaling inactivation was proposed as possible treatment for prostate cancer." (PMID 28005952, 2016). "There are a number of genes involved in prostate cancer progression, which have been reported to be downregulated in some studies and overexpressed in other studies (e.g. STAT3)." (PMID 28005952, 2016). "In prostate cancer, aberrant IL-6/STAT3 signalling is one of the most involved pathways during the transition of metastatic disease." (PMID 27435207, 2016). "CCL2 is secreted by prostate cancer cells and tumor-associated macrophages (TAM) during coculture conditions that mimic ADT and induces prostate cancer cell migration/invasion via CCL2-dependent STAT3 activation and the EMT pathways." (PMID 26701731, 2016). "Genes up-regulated in RWPE-1 cells (prostate cancer) upon expression of constitutively active form of STAT3." (PMID 27732959, 2016). "Recently, we demonstrated that iron chelators regulate the STAT3 pathway in pancreatic and prostate cancer cells through inhibition of constitutive and IL-6-induced STAT3 activation." (PMID 26125440, 2015). "Previous study suggested that saw palmetto induced growth arrest and apoptosis of prostate cancer cells by the inhibition of STAT3 signal pathway." (PMID 26788112, 2015). "In both LNCaP and PC3 cell variants higher levels of TLR9 expression and activation (by CpG ODN stimulation) correlated with increased mRNA and protein levels of IL-6, an important STAT3 activator and a contributor to prostate cancer progression." (PMID 26046794, 2015). "The inability of IFN to induce miR-21 expression in PC3 prostate cancer suggests a potential role of STAT3 in the regulation on miR-21 expression, since these cells lack the STAT3 gene." (PMID 26610525, 2015). "Taken together, our results suggest that NF-κB/RELA and STAT3 cooperate to various extents in orchestrating expression of TLR9-induced prostate cancer stem cell-related genes." (PMID 26046794, 2015). "Cancers of the prostate, pancreas and breast, as well as leukemias and melanomas, have all been reported to display constitutive activation of STAT3." (PMID 26125440, 2015). "The IPA analysis of our RNAseq data suggested NF-κB/RELA and STAT3 as top mediators of TLR9-dependent gene expression in prostate cancer cells." (PMID 26046794, 2015). "In prostate cancer, STAT3 activation correlates with Gleason score and pathological stage and modulates cancer stem cells and epithelial–mesenchymal transition." (PMID 28031890, 2015). "We demonstrate that TLR9/NF-κB/STAT3 signaling axis operates in prostate cancer cells to promote expression of tumorigenic and stem cell-related genes." (PMID 26046794, 2015). "The role of STAT3 signaling in modulating prostate cancer stem cells (PCSCs), EMT and tumor angiogenesis has only recently been investigated." (PMID 28031890, 2015). "IL-6-mediated activation of STAT3 in human prostate cancers is well documented and related to androgen-independence." (PMID 26046794, 2015). "We have reported that the glucosamine suppressed the proliferation of the human prostate carcinoma cell line DU145 through inhibition of STAT3 signaling." (PMID 24932134, 2014). "In vitro, STAT3 DNA-binding activity and constitutively active STAT3 were observed in three human prostate cancer cell lines (DU145, PC3, and LNCaP)." (PMID 25268165, 2014). "Reciprocally, in breast, skin, pancreatic, cervical, head and neck carcinoma and prostate cancer cell lines expression of constitutively active STAT3 up-regulates VEGF expression and tumor angiogenesis." (PMID 24722453, 2014).
prostate carcinoma (continued). "Our studies provide evidence that inhibiting STAT3 pathways should be considered for further exploitation in therapeutic development of prostate cancer." (PMID 25261365, 2014). "VEGF has been shown to be a direct target of STAT3 and our current studies provide novel insight into Ron-mediated vascular development in prostate cancer." (PMID 24980820, 2014). "In vitro analysis demonstrated robust STAT3 activation resulting in Bcl2-dependent survival following treatment of prostate cancer cells with HGFL." (PMID 24980820, 2014). "For prostate cancer, the main effort to target constitutive STAT3 signaling is only focused on the bulk of cancer cells at the present time." (PMID 25261365, 2014). "The purpose of the present study was to investigate the inhibitory and apoptotic effects of AG490, S3I-201 and TRAIL combinations on the JAK/STAT3 signaling pathway in a human prostatic carcinoma cell line (LNCaP)." (PMID 24520293, 2014). "In this study, we demonstrated that STAT3 contributed to the ability of prostate cancer to support angiogenesis." (PMID 25261365, 2014). "The effective elimination of the subproportion of ALDHhigh cells in the PC3M-1E8 cells and primary prostate cancer cells by Stattic suggested that these TIC-like cells were sensitive to STAT3 inhibition." (PMID 25261365, 2014). "STAT3 knockdown significantly impaired the ability of prostate cancer cells to initiate development of prostate adenocarcinoma." (PMID 25261365, 2014). "Heat shock protein 27 (Hsp27) induces IL-6 dependent and independent EMT in prostate cancer by promoting phosphorylation and nuclear translocation of STAT3, making STAT3 to bind to the Twist promoter, and activating Twist function." (PMID 24618337, 2014). "Survivin is a downstream target of the signal transducer and activator of transcription 3 (Stat3) that can be activated by IL-6 in prostate cancer." (PMID 24296978, 2014). "has anti-carcinogenic properties against colon cancer, and 6-gingerol has apoptotic effect against breast and prostate carcinoma cells via modulation of STAT3 and MAPK signaling pathway." (PMID 25241226, 2014). "IL-6 and STAT3 overexpression were seen in prostate cancer and blockade of STAT3 suppressed clonogeneity in stem cell-like cells in high grade prostate cancer patients." (PMID 24743778, 2014). "Previous studies have demonstrated that STAT3 signalling has a critical role in the tumour formation of prostate cancer and IL-6 treatment results in the activation of STAT3 in prostate cancer cells." (PMID 25112532, 2014). "Our results showed that the blockade of STAT3 significantly impaired the ability of prostate cancer cells to initiate development of prostate adenocarcinoma." (PMID 25261365, 2014). "Based on the multifaceted nature of STAT3 signaling in the progression to mCRPC, the promise of STAT3 as a therapeutic target to prevent prostate cancer progression and the variety of STAT3 inhibitors used in cancer therapies is discussed." (PMID 24722453, 2014). "B cell accumulation and STAT3 activity were also highly elevated in all other human tumor types examined, including gastric, lung, liver and prostate cancers." (PMID 23734190, 2013). "After castration, activated STAT3 has been reported to promote the transcriptional activity of unliganded androgen receptor in prostate cancer cells." (PMID 23343355, 2013). "It has been reported that STAT3 is constitutively activated in prostate cancer tissue and induction of STAT3 expression can induce a malignant change of normal prostate epithelial cells." (PMID 24205155, 2013). "We reported previously that overexpressed IL-6 and activated STAT3 signaling are critical for aggressive tumor behavior and the transition of HR prostate cancer." (PMID 23806095, 2013). "Using this same invasion assay, our lab has recently demonstrated that the invasion of prostate cancer cells toward SCM can be blocked using the STAT3 inhibitor Stattic." (PMID 24772452, 2013).
prostate carcinoma (continued). "Our findings suggest that scoparone elicits an anti-tumor effect against DU145 prostate cancer cells in part through inhibition of STAT3 activity." (PMID 24260381, 2013). "The clinical and functional implications of transcription factor STAT5A/B and STAT3 have been well established in prostate cancer." (PMID 23668334, 2013). "We further examined the effect of irradiation on IL-6/STAT3 signaling in prostate cancer in the present study." (PMID 23806095, 2013). "My N. Chau and colleagues developed a prostate cancer cell line which contained a STAT3 reporter construct for high throughput screening of STAT3 activators and inhibitors." (PMID 23704931, 2013). "All these observations demonstrate that STAT3 is an important cancer-related TF and has a prominent impact on occurrence and development of prostate cancer." (PMID 24205155, 2013). "Our model identified several transcription factors associated with prostate cancer metastasis, such as ETS2, HOXC4, STAT3, STAT5B, SOX4 and ZEB2." (PMID 23782521, 2013). "Activation of STAT3 involves phosphorylation at Tyr705, and STAT3 has been shown to be activated in prostate cancers." (PMID 23620784, 2013). "Two signaling transduction pathways, namely PI3K/AKT and JAK/STAT3 pathways, have been shown to activate AR in prostate cancer cells." (PMID 23620780, 2013). "HR prostate cancer cells had a higher expression of IL-6 and more activated STAT3, compared to TRAMP-C1 cells." (PMID 23806095, 2013). "Ni and coworkers reported that Janus kinase inhibitor, tyrphostin AG490, inhibited the constitutive activation of STAT3 and suppressed the growth of human prostate cancer cells." (PMID 24199193, 2013). "NF-kB and STAT-3 transcription factors have previously been shown to play a role in angiogenesis and invasion of prostate cancer cells." (PMID 23824300, 2013). "For example, constitutive activation of the STAT3 and NF-κB signaling pathways is found in prostate cancer cell lines and clinical samples of prostate cancer." (PMID 23940701, 2013). "Constitutive activation of STAT3 is common in melanoma, breast, head and neck, lung, pancreatic and prostate cancer." (PMID 23597096, 2013). "More recently, these bacteria have been engineered to express numerous genes, including survivin, MDM2, Neu3 and STAT3 siRNA against prostate cancer in our laboratory." (PMID 23721095, 2013). "Lymphotoxin β-induced nuclear IKKα, in conjunction with STAT3, contributes to the emergence of castration resistance and enhances hormone-free survival and metastasis of prostate cancer by an NF-κB-independent, cell autonomous mechanism." (PMID 23343355, 2013). "Our data suggests that EVs are immune to these limitations and can effectively eliminate the effects of STAT3 mediated signaling in prostate cancer." (PMID 24103426, 2013). "Sixth, the transcription factors NF-κB and STAT3, both major mediator of inflammation, are constitutively active in prostate cancer tissues." (PMID 22427843, 2012). "In agreement with our studies, PEITC has been shown to suppress STAT3 activation in prostate cancer cells." (PMID 22824293, 2012). "It has previously been shown that indirubin derivative E804 (IDR-E804) blocks signal transducer and activator of transcription-3 signaling in human breast and prostate cancer cells and inhibits Src kinase activity." (PMID 22554053, 2012). "Persistently activated STAT3 was reported to be required for maintaining the constitutive NF-κB activity in melanoma and prostate cancer cells." (PMID 22984561, 2012). "CDDO-Me also inhibited hTERT regulatory proteins such as c-Myc, Sp1, NF-κB, p-STAT-3 and p-Akt in prostate cancer cell lines." (PMID 23519253, 2012). "RM-9, a mouse prostate cancer cell line with constitutively activated STAT3, was inoculated subcutaneously in C57BL/6J mice." (PMID 22911830, 2012). "We have recently reported that UA can inhibit AKT, IKKα/β, NF-κB and STAT3 activation in androgen dependent and independent prostate cancer cell lines." (PMID 22427843, 2012).